TNF (tumor necrosis factor)
Diseases named in the same sentence as TNF in open-access papers (continued):
Sharing a sentence is not in itself a finding about the gene and the disease.
Sepsis (continued). "Cardiovascular dysfunction is one of the leading causes of death in septic shock patients, and the local source of TNF-α in the myocardium plays a critical role in cardiac failure during sepsis." (PMID 25180066, 2014). "Severe pneumonia patients treated with Xuebijing have shown decreased secretion of TNF-α, IL-6 and IL-8, similarly to patients with sepsis." (PMID 25511395, 2014). "In a clinical report of 97 consecutive patients, 56% developed sepsis with about 26 pg/mL of TNF-α 37% had 20 pg/mL of IL-1 and in 80%; 415 pg/mL of IL-6 was detected, including a LPS mean concentration of 2.6 endotoxin units (EU)/mL (1 EU/mL = 0.6 ng/mL)." (PMID 24605247, 2014). "The presence of endotoxin in the blood stream is a primary contributor of septic shock, and several proinflammatory cytokines such as TNF-α and IL-6 can contribute to cardiac dysfunction during sepsis." (PMID 25180179, 2014). "Twenty years have passed since the first patients with sepsis were included in clinical trials based on the understanding that TNF orchestrates the inflammatory response and should be the target for therapeutic intervention." (PMID 24886820, 2014). "Further, neuroimmunopathogenesis of sepsis involves peripheral release of proinflammatory cytokines (TNF-α, IL-1α, IL-1β, and IL-6) increasing blood brain barrier (BBB) permeability, generating neuroinflammation and sepsis associated sickness behaviour." (PMID 25018890, 2014). "MSCs have been shown to suppress production of pro-inflammatory cytokines and chemokines, including MIP-2(CXCL-2), CCL5, TNF, IL-6, and IL-1β, in animal models of lung injury and sepsis." (PMID 24423010, 2014). "It is well-established that cardiomyocyte TNF-α production contributes to cardiac dysfunction in sepsis 2–6 and circulating NE levels elevate significantly during sepsis 13–16." (PMID 24304472, 2014). "Both IL-1β and TNF-α appear to play important roles in endoxemia/sepsis-induced myocardial dysfunction." (PMID 25216263, 2014). "In the current study, we examined MK2-deficiency in a model of TNF or LPS-induced systemic inflammation, as well as cecal ligation and puncture (CLP)-induced sepsis." (PMID 25185746, 2014). "Previous study of group A streptococci showed that high levels of both TNF-α and IL-6 were inversely correlated with survival time in patients with sepsis." (PMID 25264876, 2014). "The release of proinflammatory cytokines (TNF-α and IL-1β) leads to cardiac depression or dysfunction following sepsis." (PMID 24959004, 2014). "Most of the harmful effects observed during sepsis have been ascribed to excessive production of inflammatory cytokines, such as TNF." (PMID 25057275, 2014). "The expression levels of TNF-α and NF-κB were significantly lower in the NaHS groups compared with those in the sepsis group (P<0.05)." (PMID 25009602, 2014). "As for the pathogenesis of cardiac dysfunction in sepsis, TNF-α can impair contractile performance in intact animals, isolated hearts, and cardiomyocytes." (PMID 25180066, 2014). "ApoE inhibited the lipopolysaccharide (LPS)-induced increase of tumor necrosis factor-α, interleukin (IL)-1β and IL-6 in serum and decreased the mortality rates of mice with sepsis." (PMID 25242054, 2014). "The sepsis-induced increase in muscle MuRF1 and atrogin-1 (markers of proteolysis) as well as TNFα and IL-6 (inflammatory cytokines) mRNA was greater in DKO than WT mice." (PMID 24945486, 2014). "TNF-α is an inflammatory marker released by activated macrophages, monocytes and neutrophils and has been shown to have a major role in both sepsis and septic AKI." (PMID 24826374, 2014). "TNF-α has a central role in normal inflammatory responses and in a wide range of pathophysiologic inflammatory disorders, including sepsis." (PMID 25180066, 2014). "Fifth, in general TNF-α serum levels are increased in systemic inflammatory response syndrome and sepsis patients." (PMID 24651840, 2014).
Sepsis (continued). "ALI and AKI occur together early in the course of sepsis and TNF-α plays a role in the early pathogenesis of both." (PMID 24265742, 2013). "Studies have shown that the administration of this cytokine induces a syndrome in animals with characteristic of sepsis, and finally treatment with anti-TNF antibody protects against the lethal effects of endotoxins in animal models." (PMID 23737945, 2013). "TNF-α and IL-1 (a term used for a family of proteins, including IL-1α and IL-1β) are among the most extensively studied cytokines in sepsis pathophysiology." (PMID 23853427, 2013). "It was suggested that low miR-150 serum levels identify septic disease in these patients and that miR-150 levels correlate with classical prognosis scores such as SOFA or established markers for sepsis and inflammation such as TNF, IL-10 or IL-18." (PMID 23372743, 2013). "A number of inflammatory cytokines, including IL-6, IL-10, IL-1, and TNF-α were involved in sepsis, which contributes to tissue and organ damage." (PMID 24324295, 2013). "Different strategies to inhibit TNFα in patients with sepsis and chronic inflammatory conditions have shown contrasting outcomes." (PMID 24236088, 2013). "TNF-α, IL-6 and IL-1β are the most important endogenous mediators in the sepsis process, the measurement of which can be helpful in the determination of sepsis severity." (PMID 24250599, 2013). "For example, T cells from HIF1α-deficient mice released significantly more tumor necrosis factor and IFN-γ after T cell receptor activation than wildtype T cells and mice showed an enhanced survival rate in a sepsis model." (PMID 23675474, 2013). "The pathogenesis of sepsis involves a complex process of cellular activation at multiple levels resulting in release of pro-inflammatory cytokines such as TNF-α, IL-1β, high-mobility group box 1(HMGB1) and anti-inflammatory cytokines, such as IL-10." (PMID 23497622, 2013). "Since dexamethasone inhibits release of TNFα from whole blood of patients with sepsis, we investigated the role of TNFα on the observed effect of dexamethasone inhibition of TREM-1/sTREM-1 expression." (PMID 24350219, 2013). "TNF-α is one of the most important pro-inflammatory cytokines that is highly elevated during inflammation in sepsis." (PMID 24086305, 2013). "We and other investigators recently observed that ADN binds to LPS to decrease ADN levels in rats with polymicrobial sepsis, with a reciprocal increase in TNF-α levels." (PMID 23520452, 2013). "IL-8 and TNF-α cytokines levels were relatively low in control rats; however, both cytokines were increased in the sepsis-control groups, with the enhancement being most significant by 12 hrs for IL-8 and 24 hrs for TNF-α after inoculation." (PMID 24369483, 2013). "Unlike terminally differentiated macrophages and monocytes, these cells produce large amounts of IL-10 and TNF-alpha after sepsis or trauma." (PMID 24371374, 2013). "A role for TNF-α and IL-1 in sepsis was demonstrated in numerous reports, including both experimental animal models of septic shock and studies in humans with sepsis." (PMID 23853427, 2013). "To investigate the role of βGalT1 in TNF-mediated diseases such as sepsis and IBD, we generated mice overexpressing βGalT1 (TG) and subjected them to TNF-induced SIRS and DSS-induced colitis." (PMID 24339869, 2013). "LPS infusion induced a systemic inflammatory response similar to that encountered during the very early stages of sepsis, with fever, increased heart rate, tachypnoea and hyperventilation, leukocytosis, as well as elevated TNF-α and IL-6 levels." (PMID 24131656, 2013). "During sepsis, unregulated inflammatory cytokines, including the inflammatory cytokine TNF-α, can result in organ failure and severe pathologic inflammation." (PMID 24020447, 2013).
Sepsis (continued). "TNF, being an endogenous pyrogen, is able to induce fever, apoptotic cell death, sepsis through IL-1 and 6 production, cachexia and inflammation, as wells as inhibit tumorigenesis and viral replication." (PMID 23426606, 2013). "Previous studies confirmed that the HES 130/0.4 significantly attenuated inflammation and subsequent ALI by decreasing TNF-α and other cytokines activation in a rat sepsis model." (PMID 23741323, 2013). "In patients with sepsis, TNF-α is the first proinflammatory cytokine that is released, followed by others including IL-1, IL-6, and IL-8." (PMID 24363773, 2013). "Upregulated IL-19 in sepsis induces lung and liver tissue injury by inducing apoptosis and the production of IL-6, IL-8, TNF-α, and reactive oxygen species (ROS)." (PMID 23710200, 2013). "It is triggered by cytokines IL-6, TNF-α, and so forth and is a late marker of neonatal sepsis which increases evidently at 24 h after sepsis onset." (PMID 23984377, 2013). "Tumor necrosis factor (TNF) plays a key role in sepsis due to its ability to trigger respiratory burst and nitric oxide production while diminishing peripheral vascular resistance, leading to disseminated intravascular coagulation and multiple organ failure." (PMID 23548047, 2013). "At the time of diagnosis, serum IL-1beta, IL-6, IL-8, and TNF-alpha levels of culture-proven sepsis were significantly higher than those of the control groups (P<.05)." (PMID 23869218, 2013). "Central to the controversy is the apparent failure of clinical trials of anti-TNF-α therapies in sepsis, which were based on animal studies." (PMID 24265742, 2013). "For example, it has been reported that the administration of anti-IL-6 antibodies improves survival in sepsis; while TNF blockade inhibits hepatic expression of iNOS and nitrotyrosine in mice with endotoxic shock." (PMID 23548047, 2013). "Dexamethasone is the corticosteroid with the greatest anti-inflammatory activity, and inhibits the ex vivo production of TNFα, IL-6, IL-8, and IL-12p40 by LPS-stimulated whole blood from patients with sepsis in a dose-dependent manner." (PMID 24350219, 2013). "Enhanced glucose release, reduced glucose consumption and increased free fatty acids indicate a catabolic state in sepsis, which is further exacerbated by the release of cytokines such as TNFα (cachectin)." (PMID 23825606, 2013). "Levels of IL-6, IL-10 and TNF-α were predictive for fatal outcome in patients with sepsis, while IL-10 levels were predictive for survival." (PMID 23520553, 2013). "Artesunate was able to protect mice subjected to sepsis by decreasing serum IL-6 and TNF levels via inhibition of Toll-like receptors expression and NF-κB activation in peritoneal macrophages." (PMID 24180288, 2013). "In vivo models of sepsis have demonstrated that pretreatment with sevoflurane decreased TNF-α and IL-6." (PMID 23552565, 2013). "This is, in part, because levels of circulating cytokines such as TNF-α are much lower in patients with sepsis than in the animal models." (PMID 24098750, 2013). "In early studies, the efficacy of anti-TNF-α and IL-1 receptor-antagonist therapies in human sepsis were disappointing, partly because TNF-α and IL-1β were released early in the development of sepsis, thereby limiting the effect of such therapies." (PMID 23497622, 2013). "Soluble tumor necrosis factor-α (TNF-α) had been established as an important crucial cytokine in inflammatory states including sepsis and SIRS, but its frequent monitoring is helpful to reveal the onset and to predict the outcome of septic patients." (PMID 24175285, 2013). "IL-10 is known to be an important regulator of inflammation in sepsis, and plays an important role in down-regulating the expression of monocyte-derived TNF-α and IL-1." (PMID 24069500, 2013).
Sepsis (continued). "TNF, as an endogenous pyrogen, is able to induce fever, induce apoptotic cell death, sepsis (through IL-1 and IL-6 production), cachexia and inflammation, as well as inhibit tumorigenesis and viral replication." (PMID 24137202, 2013). "Application of this technique in further experiments showed, that classical sepsis mediators, such as LPS, TNF-α, or thrombin alone are sufficient to rapidly deteriorate the eGC, as observed during murine endotoxemia." (PMID 24278345, 2013). "Increasing evidence has demonstrated that TNF-α and NO are important factors contributing to myocardial dysfunction during sepsis." (PMID 23691077, 2013). "In our study we can show a hyporesonsiveness in severe sepsis seen as reduced TNF inducibility to E. coli endotoxin and to S. aureus antigen (lipotheichonic acid, LTA)." (PMID 23414215, 2013). "For example, the combination of IL-1 and TNF induces septic shock, resulting in a synergistic potentiation of sepsis." (PMID 23922826, 2013). "Elevated IL-6 concentrations are measured in many acute conditions, such as burns, major surgery and sepsis, and peak subsequent to TNF-α and IL-1 concentrations." (PMID 23853427, 2013). "Induction of IL-19 occurs in severe sepsis and postcardiopulmonary bypass patients with a parallel shift that corresponds to the changes in TNF-α and IL-6." (PMID 23710200, 2013). "A transient significant elevation of TNF-α was observed in sepsis and SIRS patients during the 3rd and 5th days of ICU stay in relation to their admission mean values." (PMID 24175285, 2013). "In acute injuries and diseases such as burns, surgeries, and sepsis, the contents of TNF-α, IL-1β, and IL-6 significantly increase." (PMID 23586067, 2013). "Similar to TNF-α, low or undetectable IL-6 serum levels are reported for some patients with severe bacterial infections, which limits its usefulness for ruling out sepsis and bacteremia." (PMID 23690657, 2013). "Previous studies have shown that HMGB-1 differs from early innate proinflammatory cytokines, such as TNF and IL-1, in endotoxaemia and sepsis models." (PMID 24188108, 2013). "This is a critical point as anti-TNF-α mAb treatment increases sepsis mortality in the clinic, since some degree of TNF-α production and consequent early pro-inflammatory signalling is essential for an effective immune response." (PMID 23781123, 2013). "ST36 acupuncture has been shown to inhibit TNF-α production, attenuate trauma-induced immunosuppression, and reverse sepsis-induced neutrophil igration impairment in septic rats." (PMID 23662144, 2013). "TNFα (tumour necrosis factor α) is an early mediator in the systemic inflammatory response to infection and is therefore a therapeutic target in sepsis." (PMID 23863106, 2013). "In sepsis, tumor necrosis factor (TNF) is the key factor triggering respiratory burst, tissue injury and disseminated coagulation." (PMID 23548047, 2013). "In the present study, we investigated the suppressive effect of XBJ on the development of A. baumannii-induced sepsis in rats by not only increasing the expression of annexin A1 but also decreasing the serum release of either IL-8 or TNF-α." (PMID 24369483, 2013). "TNF-α and IL-6 are cytokines elevated in sepsis both in humans and animals and their production is tightly related both to NF-kB activation and ROS levels." (PMID 24098806, 2013). "ELISA of lung homogenates revealed similar levels of TNF-α between groups at six hours but decreased levels of TNF-α at 24 hours post sepsis onset in propranolol treated rats compared to control rats (P <0.05, 95% CI -293.4 to -1.7)." (PMID 24020447, 2013). "This is certainly known to be the case with eNOS mRNA in hypoxia and in the presence of high TNF-α, both characteristic of sepsis." (PMID 23781123, 2013). "In contrast, systemic serum levels of pro-inflammatory cytokines of TNF-α and IL-6 were elevated during the first days after induction of sepsis and the creation of the wound verifying the septic state of the mice." (PMID 24086305, 2013).
Sepsis (continued). "AZD9773 is an ovine-derived, polyclonal anti-TNFα Fab fragment derived from a pool of serum and currently being developed as a treatment for severe sepsis and septic shock." (PMID 23863106, 2013). "Production of IgM and of TNFα was significantly lower at all stages of sepsis compared with healthy controls." (PMID 24144038, 2013). "Plasma TNF-α levels were also decreased in propranolol treated rats when compared with untreated septic control rats (P <0.05) at 24 hours post sepsis onset." (PMID 24020447, 2013). "Gene expression of TNF in severe sepsis was down-regulated as expected due to the immunoparalysis of circulating monocytes." (PMID 24350219, 2013). "The first group is the early proinflammatory mediators, such as TNF-α and IL-1β, which are induced within hours after the induction of sepsis." (PMID 24098466, 2013). "It has been demonstrated, that the pro-inflammatory cytokines Interleukin (IL)-1 and tumor necrosis factor (TNF) α can elicit pathological responses similar to clinical features of sepsis." (PMID 24356325, 2013). "In summary, our data indicate that classical sepsis mediators, such as LPS, TNF-α, or thrombin alone are sufficient to rapidly deteriorate the eGC in vitro." (PMID 24278345, 2013). "In sepsis the dysregulated host inflammatory response by the exuberant release of cytokines in particular TNFα into the circulation worsens the metabolic state of septic patients leading to metabolic alterations such as transient type II diabetes." (PMID 23825606, 2013). "Tumor necrosis factor-α (TNF-α) is one of the most potent pro-inflammatory cytokines identified in sepsis." (PMID 23710641, 2013). "Consistent with previous studies, our data showed that the increased serum and tissue TNF-α and IL-6 levels in mice with early stages of sepsis were down-regulated by DXM." (PMID 24244697, 2013). "Serum concentrations of TNF-α are elevated in sepsis, and animal models of sepsis, and a correlation between plasma concentrations of TNF-α and myocardial dysfunction has been established." (PMID 24303157, 2013). "LPS induces expression of pro-inflammatory cytokines, such as TNF-α and IL-6, which are involved in the pathogenesis of sepsis and are also an early predictors of organ dysfunction." (PMID 23564188, 2013). "Our observation that sepsis induces a reduced level in local TNF-α production is further supported by the notion that invading neutrophils and macrophages in wounds are depleted in septic animals whereas the neutrophil counts in peripheral blood are elevated." (PMID 24086305, 2013). "Investigators added to substantiate the link between sepsis and TNF by utilizing anti-TNF monoclonal antibodies to counteract the circulating TNF and thereby put off its adverse effects on cardiovascular system." (PMID 24198887, 2013). "Anti-PD-L1 antibody administration prevented sepsis-induced depletion of lymphocytes, increased tumor necrosis factor (TNF)-α and interleukin (IL)-6 productions, decreased IL-10 production, and enhanced bacterial clearance." (PMID 24324295, 2013). "Because ω-3 PUFA supplemented mice suffered increased mortality, we also examined serum IL-15, a cytokine shown to induce sepsis, as well as TNF-α." (PMID 23405155, 2013). "During the early phase of sepsis, many proinflammatory cytokines, including tumor necrosis factor (TNF)-α and interleukin (IL)-1, are released by macrophages in response to endotoxin." (PMID 23532259, 2013). "In 1975, Carswell described the pivotal role of tumor necrosis factor, as one of the earliest monokines, in severe sepsis." (PMID 24371374, 2013). "Meanwhile, several studies demonstrate that macrophages also produce IL-1β, TNF-α, and IL-6 during sepsis." (PMID 23675299, 2013). "Clinically relevant doses of PCT, similar to those achieved in sepsis, induced the secretion of the pro-inflammatory cytokines TNFα, IL-1β and IL-6 in whole human blood cells in vitro." (PMID 23937962, 2013).